PIEZO1 (piezo type mechanosensitive ion channel component 1 (Er blood group))
Diseases named in the same sentence as PIEZO1 in open-access papers (continued):
Sharing a sentence is not in itself a finding about the gene and the disease.
hypertensive nephropathy (1 paper, 2024). Kidney damage that results from chronically elevated blood pressure; complications include glomerular damage resulting in proteinuria and hematuria. "Previously published data show an increase of Piezo1 levels in podocytes in a hypertensive nephropathy mouse model and lupus nephritis." (PMID 39548228, 2024). "Moreover, recent studies confirmed expression of Piezo1 in podocytes and also showed increased Piezo1 expression in podocytes in experimental hypertensive nephropathy and lupus nephritis." (PMID 39548228, 2024). "Analysing publicly available data from the Kidney Precision Medicine Project (KPMP) revealed an increase of Piezo1 in podocytes in CKD samples, which is in line with data obtained from experimental hypertensive nephropathy and lupus nephritis mouse models." (PMID 39548228, 2024).
infarction (1 paper, 2025). A localised pathological necrosis of tissue resulting from obstruction of the blood supply usually by a thrombus, an embolus, or vascular torsion. "Masson's trichrome staining revealed similar results, that the reversal of Piezo1 expression reduced the infarction size to 18.9% and increased the LV wall thickness to 1.47 mm 4 weeks post‐MI, compared to 24.4% and 1.0 mm in the MI+shCtrl group." (PMID 40344385, 2025). "Although the elevated Piezo1 level did not significantly upregulate Col1a1, histological evaluations showed overexpression of PIEZO1 resulted in a larger infarction size (19.6%) and smaller LV wall thickness (1.7 mm) compared to MI+P (17.4%, 2.0 mm) and MI+P+oeCtrl (17.3%, 2.0 mm)." (PMID 40344385, 2025).
Interstitial cardiac fibrosis (1 paper, 2022). A type of myocardial fibrosis characterized by excessive diffuse collagen accumulation concentrated in interstitial spaces. "We evaluated interstitial cardiac fibrosis in response to pressure overload 14 d after TAC in Piezo1 KO hearts and α-MHC-MCM+/− hearts using Masson’s trichrome staining." (PMID 39195867, 2022). "There was increased interstitial cardiac fibrosis in α-MHC-MCM+/− TAC hearts when compared with their sham controls (P < 0.001), but there was no increase in cardiac fibrosis in Piezo1 KO hearts after TAC." (PMID 39195867, 2022).
interstitial cystitis (1 paper, 2021). A rare chronic debilitating urogenital disease characterized by urinary frequency, urgency, and pelvic pain. "Aberrant activation of PIEZO1 has been suggested to play a role in clinical bladder pathologies like partial bladder outlet obstruction and interstitial cystitis/bladder pain syndrome (IC/BPS)." (PMID 35295484, 2021). "Specifically, using a psychological/physical stressor or a naturally occurring disease model, like feline interstitial cystitis, could determine if Piezo1 is indeed a possible target for therapeutic treatment." (PMID 35295484, 2021). "In addition to their role in bladder function, PIEZO1 and other MSCs have been shown to contribute to bladder dysfunction in models of interstitial cystitis/bladder pain syndrome (IC/BPS)." (PMID 35295484, 2021).
intracranial hypertension (1 paper, 2024). A finding characterized by increased cerebrospinal fluid pressure within the skull. "Intracranial hypertension caused increased abundance of Bax and cleaved caspase 3, accompanied with decreased protein expression of Bcl‐2, both of which were partially diminished by Piezo1 inhibitor GsMTx4." (PMID 39328029, 2024). "Activation of Piezo1 by intracranial hypertension induced neuronal apoptosis via activating the Hippo pathway." (PMID 39328029, 2024). "Intracranial hypertension induced Piezo1 protein expression, which was markedly suppressed by GsMTx4 at 1 and 5 μM." (PMID 39328029, 2024). "The findings appeared to contradict our conclusion that neuronal apoptosis was induced by Piezo1 activation through intracranial hypertension." (PMID 39328029, 2024). "Activation of Piezo1 by intracranial hypertension induced neuronal apoptosis via activating the Hippo pathway in primary neurons." (PMID 39328029, 2024). "This study aimed to investigate the effect of Piezo1 on neurons in response to intracranial hypertension." (PMID 39328029, 2024). "In this study, we found that intracranial hypertension simulated by the pressurizing device succeeded in increasing Piezo1 expression in a pressure‐dependent and time‐dependent manner when primary neurons were subjected to the hypertensive environment." (PMID 39328029, 2024). "In vitro, intracranial hypertension mimicked by the pressurizing device induced Piezo1 expression, resulting in Hippo pathway activation and neuronal apoptosis." (PMID 39328029, 2024). "Neurons were pretreated with Piezo1 inhibition followed by intracranial hypertension treatment, and then apoptosis‐related proteins were detected." (PMID 39328029, 2024). "Then, we verified the effect of Piezo1 activation on neuronal apoptosis and the Hippo pathway activation in respond to intracranial hypertension in vitro." (PMID 39328029, 2024). "Piezo1 knockdown attenuated intracranial hypertension‐induced increased protein of Bax and cleaved caspase 3, and reversed protein level of Bcl‐2 to control levels." (PMID 39328029, 2024). "Intracranial hypertension induced Piezo1 expression, neuronal apoptosis, and the Hippo pathway activation; the Hippo signaling pathway is involved in Piezo1 activation‐induced neuronal apoptosis in respond to intracranial hypertension." (PMID 39328029, 2024). "Intracranial hypertension also increased the expression of p‐LATS1 and p‐YAP, which was partially prevented by Piezo1 knockdown." (PMID 39328029, 2024). "GsMTx4 was not a specific Piezo1 antagonist, so lentiviral transduction of shRNA was introduced to elucidate the function of Piezo1 in neurons in respond to intracranial hypertension." (PMID 39328029, 2024).
ischemic cardiomyopathy (1 paper, 2025). Ischemic cardiomyopathy is a cardiomyopathy in which a weakness in the muscle of the heart due to inadequate oxygen delivery to the myocardium with coronary artery disease being the most common cause. "Increased mechanical stress and PIEZO1 upregulation are observed in ischemic cardiomyopathy myocardium." (PMID 40344385, 2025). "Our study has established the critical role of PIEZO1 in the pathogenesis of ischemic cardiomyopathy (ICM), primarily driven by increased mechanical stress on the infarcted tissue." (PMID 40344385, 2025).
itch (1 paper, 2022). "The question remains as to why PIEZO1 transduces mechanical itch when PIEZO2 is expressed in somatosensory neurons and is exquisitely sensitive to mechanical stimuli." (PMID 35732741, 2022). "This specific expression pattern suggested that PIEZO1 has a role in itch." (PMID 35732741, 2022). "We subsequently investigated whether the activation of PIEZO1 can trigger acute itch." (PMID 35732741, 2022). "Finally, we asked whether acute inhibition of PIEZO1 could alleviate mechanical itch and itch sensitization." (PMID 35732741, 2022).
joint diseases (1 paper, 2025). "In the context of bone and joint diseases, the molecular mechanisms mediated by Piezo1 are closely associated with mechanical stress stimulation." (PMID 40753437, 2025).
lentivirus infection (1 paper, 2021). Virus diseases caused by the Lentivirus genus. "Moreover, we utilized only normal MC3TC cells as the control, and Piezo1 negative-control shRNA should be used as the control group to minimize the effect of lentivirus infection on the biology of MC3T3-E1 cells in future studies." (PMID 33692342, 2021).
lipodystrophy (1 paper, 2019). A congenital or acquired disorder characterized by abnormal loss or redistribution of the adipose tissue in the body. "The reduced pgWAT mass and fatty liver in adipose-Piezo1−/− mice may represent mild lipodystrophy." (PMID 31263454, 2019).
liver cirrhosis (1 paper, 2025). "Piezo1 in the peritoneal endothelium/LSECs contributes to the formation of portal hypertensive ascites via the NF-ĸB−AQP1 pathway in liver cirrhosis." (PMID 41034523, 2025). "In liver cirrhosis, Piezo1 activation in endothelial cells may lead to ascites by increasing AQP1 expression, a protein that helps water move across cell membranes." (PMID 41034523, 2025).
macular degeneration (1 paper, 2023). Loss of vision in the central portion of the retina (macula), secondary to retinal degeneration. "Pharmacological inhibition of PIEZO1, MAPK, and actomyosin prevented degenerative pathology, whereas the activation of PIEZO1 increased cellular extrusion and degeneration, presenting viable molecular targets for the therapy of macular degeneration." (PMID 37146581, 2023).
malignant glioma (1 paper, 2020). A grade III or grade IV glioma arising from the central nervous system. "Taken together, the results indicated that high PIEZO1 expression is closely associated with highly malignant gliomas." (PMID 32999349, 2020).
Marfan syndrome (1 paper, 2026). A disorder of the connective tissue. "In a recent study, reduced levels of Piezo1 and autophagy were observed in patients and mice with Marfan syndrome (MFS)." (PMID 41507149, 2026).
memory impairment (1 paper, 2024). "This evidence verifies the role of increased PIEZO1 signaling in sleep deprivation‐induced memory impairment." (PMID 37485782, 2024). "Sleep deprivation increases PIEZO1/calpain signaling activity in the basal forebrain and induces short‐ and long‐term fear memory impairments." (PMID 37485782, 2024). "Our previous study demonstrated that acute sleep deprivation increases the enzymatic cleavage of TrkB‐FL, a receptor for brain‐derived neurotrophic factor (BDNF), through activation of the basal forebrain PIEZO1/Ca2+/calpain pathway, leading to curtailed BDNF signaling and memory impairments." (PMID 37485782, 2024).
metastatic disease (1 paper, 2025). "Future studies examining PIEZO1 activation and associated signalling in compressed tumour regions or perivascular niches within clinical specimens will be critical to validate the physiological relevance of this mechanism and assess its translational potential in metastatic disease." (PMID 40890143, 2025). "Furthermore, targeting PIEZO1 or biophysical mechanisms that precede PIEZO1 activation (e.g., capillary-like constrictions) could prove a therapeutic avenue in combating metastatic disease." (PMID 40890143, 2025).
methemoglobinemia (1 paper, 2024). An inherited or acquired condition characterized by abnormally increased levels of methemoglobin in the blood. "A left shift of the oxygen dissociation curve or when venous P50 < 24 mm Hg, is a good screening test for high oxygen affinity Hgb variants, but can also indicate 2,3-bisphosphoglycerate deficiency, methemoglobinemia or PIEZO1 variants." (PMID 39309680, 2024).
myeloid leukemia (1 paper, 2021). A clonal proliferation of myeloid cells and their precursors in the bone marrow, peripheral blood, and spleen. "Firstly, we used a specific transcriptome database (BioGPS, The Scripps Research Institute, La Jolla, CA, USA) to assess the level of PIEZO1 gene expression in the human myeloid leukemia K562 cell line." (PMID 34360605, 2021). "In the current study, we used the human myeloid leukemia K562 cell line as a suitable model to examine chemically induced Piezo1 activity with the use of the patch-clamp technique in various specific modes." (PMID 34360605, 2021). "We identified, for the first time, functionally active endogenous Piezo1 channels stimulated by the selective chemical agonist Yoda1 in human myeloid leukemia cells." (PMID 34360605, 2021).
oligodendroglioma (1 paper, 2025). A well-differentiated (WHO grade II), diffusely infiltrating neuroglial tumor, typically located in the cerebral hemispheres. "Grade II oligodendrogliomas with IDH1 mutation and 1p/19q co-deletion had the lowest level of Piezo1 protein expression." (PMID 40061015, 2025).
ovarian serous cystadenocarcinoma (1 paper, 2022). A malignant serous cystic epithelial neoplasm arising from the ovary. "PIEZO1 protein levels were significantly higher in KIRC (p < 0.001), GBM (p < 0.0001), HNSC (p < 0.0001) and PAAD (p < 0.0001) and significantly lower in COAD (p < 0.05), LIHC (p < 0.0001), LUAD (p < 0.0001), ovarian serous cystadenocarcinoma (OV) (p < 0.0001) and UCEC (p < 0.05)." (PMID 35747124, 2022).
overnutrition (1 paper, 2023). An imbalanced nutritional status resulting from excessive intake of nutrients. "In mature adipocytes, loss of Piezo1 promotes adiposity by increasing adipocyte volume with overnutrition, though this is partially offset by a reduction in adipocyte number." (PMID 36749637, 2023). "Our results and data from TRPV4 and Piezo1 mouse models support the overarching notion that adipocyte mechano-signaling regulates systemic metabolism, especially under conditions of overnutrition." (PMID 36749637, 2023).
paraganglioma (1 paper, 2025). A benign or malignant neoplasm arising from paraganglia located along the sympathetic or parasympathetic nerves. "In PCPG, patients with paraganglioma exhibited higher PIEZO1 expression." (PMID 40977743, 2025).
pericardial effusion (1 paper, 2025). Fluid collection within the pericardial sac, usually due to inflammation. "Moreover, adolescent onset of pericardial effusion occurred in humans carrying a single disruptive PIEZO1 gene variant." (PMID 40721314, 2025). "These embryos show pericardial effusion, suggesting importance of PIEZO1 in the physiological control of fluid volume around the heart." (PMID 40721314, 2025).
perinatal disease (1 paper, 2025). A condition affecting an unborn or newly born individual, where the perinatal period is defined in humans as commencing at 22 completed weeks (154 days) of gestation and ending seven completed days after birth. "There was no NIFH or other perinatal disease in the GLD08 individuals, contrasting with the NIFH in GLD07 and GLD09 and the suggestion that PIEZO1 variants are the most common monogenic etiology of NIFH." (PMID 40792030, 2025).
polycystic kidneys (1 paper, 2021). "Otherwise, YAP might cooperate with PIEZO1 in enhancing the proliferation of dilated cells, as YAP is known to be involved in the formation of polycystic kidneys via enhancement of cell proliferation." (PMID 33712686, 2021).
preeclampsia (1 paper, 2023). Preeclampsia is a hypertensive disorder of pregnancy that is characterized by new-onset hypertension with proteinuria presenting after 20 weeks of gestation, and depending on mild or severe forms may initially present with severe headache, visual disturbances, and hyperreflexia. "Moreover, given the character of this channel and its contribution to the relaxation of UA in pregnancy, further studies are needed to elucidate whether a dysfunctional Piezo1 might be implicated in the pathophysiology of preeclampsia." (PMID 37324378, 2023).
prune belly syndrome (1 paper, 2024). "Here, authors identify PIEZO1 human mutations in Prune Belly Syndrome." (PMID 38184690, 2024).
Psoriasiform dermatitis (1 paper, 2025). A skin abnormality characterized by redness and irritation, with thick, red skin that displays flaky, silver-white patches (scales). "WT mice, bearing intact PIEZO1 alleles (PIEZO1+/+), upon IMQ application, displayed pronounced psoriasiform dermatitis, starkly contrasting the phenotype of untreated controls." (PMID 40495117, 2025).
Pulmonary hypoplasia (1 paper, 2023). "In contrast, tracheal occlusion in in vivo mouse model was an inductor of α-SMA and MLC2 expression at the later canalicular stage, suggesting that the PIEZO1/PIEZO2 pathway may be a potential target for the treatment of fetal pulmonary hypoplasia." (PMID 36740669, 2023).
pulpitis (1 paper, 2024). Inflammation of the dental pulp. "Therefore, our data revealed that PIEZO1 might be associated with inflammatory markers, implying that PIEZO1 presumably involved inflammatory processes in irreversible pulpitis." (PMID 38627713, 2024). "Overall, these data revealed that PIEZO1 expression increased while PIEZO2 expression decreased in irreversible pulpitis." (PMID 38627713, 2024). "Given that PIEZOs play a vital role in inflammation and pain, the current study assumed that PIEZO expressions were altered in irreversible pulpitis, and primarily compared expression patterns of PIEZO1 and PIEZO2 between irreversible pulpitis and normal pulp." (PMID 38627713, 2024). "This study demonstrated the upregulation of PIEZO1 and the downregulation of PIEZO2 in irreversible pulpitis and revealed the potential relation of PIEZO1 and PIEZO2 to inflammation and pain." (PMID 38627713, 2024). "Therefore, PIEZO1 might also mediate the conversion of mechanical signals to inflammatory signals in irreversible pulpitis, but it requires further confirmation." (PMID 38627713, 2024). "Collectively, these results suggested the potential roles of PIEZO1 and PIEZO2 in inflammation and pain in irreversible pulpitis, which pave the way for further investigations aimed at clarifying the underlying mechanisms and achieving corresponding clinical outcomes for irreversible pulpitis." (PMID 38627713, 2024).
renal carcinoma (1 paper, 2025). A carcinoma arising from the epithelium of the renal parenchyma or the renal pelvis. "While our findings support the prognostic relevance of PIEZO1 in renal cancer, the underlying biological mechanisms remain to be fully elucidated." (PMID 40724850, 2025). "It would also be of value to explore the interaction of PIEZO1 with known renal cancer drivers, such as VHL, HIF-1α, or mTOR, and to assess its impact on angiogenesis, metabolic regulation, and immune cell infiltration." (PMID 40724850, 2025).
Robinow syndrome (1 paper, 2019). Robinow syndrome (RS) is a rare genetic syndrome characterized by limb shortening and abnormalities of the head, face and external genitalia. "Although potentially interacting pathways were not clear in the chick model, the implication of YAP/TAZ and PIEZO1 downstream of WNT5A suggests that multiple processes are likely affected by mutations that cause Robinow syndrome." (PMID 30979871, 2019).
rotator cuff tear (1 paper, 2023). "We hypothesized that a massive rotator cuff tear in a mouse model increases PIEZO1 expression and activity, making chondrocytes susceptible to mechanical injury." (PMID 37731766, 2023). "The role of PIEZO1 in rotator cuff tendon homeostasis, pathology, and repair remains unknown, and future studies to investigate the rotator cuff tendons in addition to the glenohumeral articular cartilage would enhance our understanding of PIEZO1 in a massive rotator cuff tear." (PMID 37731766, 2023).
thyroid tumor (1 paper, 2019). A benign or malignant neoplasm affecting the thyroid gland. "Similar to LC, the expression of PIEZO1 is also down-regulated in radiation-induced thyroid tumors." (PMID 30745454, 2019).
uremia (1 paper, 2025). A clinical syndrome associated with the retention of renal waste products or uremic toxins in the blood. "Our research aimed to explore if CMPF, at concentrations found in uremia, interacts with PIEZO1 located on RBCs, increases icCa2+ and induces eryptosis." (PMID 39568068, 2025). "To test this hypothesis, we explored if CMPF, at concentrations found in uremia, interacts with PIEZO1 located on RBCs, increases intracellular calcium (icCa2+), and induces eryptosis." (PMID 39568068, 2025).
ureteral stone (1 paper, 2024). "Considering that human ureter is the optimal model for ureter pharmacology, Piezo1 and TRPV2 channels may present promising pharmacological targets to improve ureteral stone passage as well as treatment of stent-associated symptoms." (PMID 38989142, 2024).
vaginal endometriosis (1 paper, 2026). "In ectopic endometriosis, there was an increase in the intensity of Piezo1 regardless of location; Piezo2 only showed a net increase in the ovarian and vaginal endometriosis foci." (PMID 41594706, 2026).